INS (insulin)
Diseases named in the same sentence as INS in open-access papers (continued):
Sharing a sentence is not in itself a finding about the gene and the disease.
type 2 diabetes (continued). "GPR139 homolog GPR142 shares the activation by L-Trp and L-Phe but is mainly expressed in the pancreas and gut, where it regulates insulin and incretin secretion, respectively, making GPR142 a potential target in type II diabetes." (PMID 34943862, 2021). "Type 2 Diabetes mellitus (T2DM) is a ‘silent disease’ characterized by hyperglycaemia and reduced insulin function." (PMID 34277977, 2021). "In the study on human type II diabetes, RSG improved glucose utilization, promoted the expression of IRS‐1 and GLUT‐4, and improved insulin sensitivity." (PMID 33650786, 2021). "During infusion of the high dose of insulin, a decrease in GIR occurred in the individuals with type 2 diabetes, following MR blockade compared to before MR blockade." (PMID 34350730, 2021). "Type 2 diabetes mellitus (T2DM) is one of the most common chronic metabolic disorders and is characterized by hyperglycemia resulting from the combination of insulin resistance and inadequate insulin secretion." (PMID 33808194, 2021). "In this circumstance, the ALDH2 activator Alda-1 still potentiated the insulin secretion of MIN6 cells in both low and high glucose concentrations, suggesting a potential for the treatment of type 2 diabetes subjects." (PMID 34680107, 2021). "Type 2 diabetes (T2DM) is characterized by insulin resistance; affected individuals cannot utilize insulin." (PMID 33504109, 2021). "Therefore, the various genetic loci that were identified thanks to very large GWAs, mainly involved in insulin secretion rather than in insulin sensitivity, confer a modest susceptibility risk to develop type 2 diabetes, whereas obesity represents the strongest predictor." (PMID 33555509, 2021). "Biological processes involved in PD share common features with obesity and type 2 diabetes mellitus (T2DM), including the dysregulation of insulin signaling in the brain." (PMID 33632120, 2021). "Accordingly, it has been shown that fecal levels of the SCFAs propionate and acetate, as well as of total SCFAs, are inversely correlated with insulin levels and HOMA-IR in patients with type 2 diabetes." (PMID 34681797, 2021). "It has been proposed that non-canonical insulin signaling might be mediated by the actions of these IGs, offering new alternatives for the treatment of diseases linked to carbohydrate metabolisms such as insulin resistance and Type 2 Diabetes." (PMID 34209137, 2021). "Here, we report for the first time that insulin induces an increment of RVR and a reduction of glomerular blood supply in type 2 diabetes." (PMID 34481498, 2021). "Likewise, overexpression of NGBR in the liver reduced ER stress and increased insulin sensitivity in high-fat diet (HFD)/streptozotocin (STZ)-treated mice tissues, suggesting that hepatic NGBR may be necessary to maintain insulin sensitivity and prevent type 2 diabetes (T2D)." (PMID 35111067, 2021). "We also determined whether cocoa-induced improvements in vascular responses translated into improved insulin/glucose metabolic responses; a hypothesis worthy of investigation since chronic intake of high dose cocoa flavanols can improve metabolic outcomes in type II diabetics." (PMID 34068170, 2021). "For example, anthocyanins from black soybeans increased insulin sensitivity by activating AMPK in skeletal muscle and liver in a type 2 diabetic mouse model." (PMID 34684731, 2021). "Based on rat models of type 2 diabetes, researchers found that oral administration of DSF increased insulin levels, improved glucose tolerance and reduced blood glucose and cholesterol levels in diabetic rats." (PMID 35185542, 2021). "An RCT showed the effect of three months of supplementation with 13 gr/d marine collagen on improvement of FBG, insulin, hemoglobin A1c, hs-CRP, free FAs, and nitric oxide (NO) in patients with type 2 diabetes compared to the control group." (PMID 34405148, 2021).
type 2 diabetes (continued). "After 3 years of tubeless insulin pump therapy, the frequency of DKA, SH (Level 3), and SH (coma) decreased to 2.2%, 4.1%, and 0.5%, respectively." (PMID 33684335, 2021). "In general, proinflammatory proteins reduce insulin signaling, contributing to the establishment of insulin resistance in different tissues and collaborating with the development of type 2 diabetes mellitus (T2DM) in obese subjects." (PMID 34203825, 2021). "Type 2 diabetes mellitus (T2DM) is a severe life-threatening health problem characterized by beta-cells dysfunction, insulin resistance, and high blood glucose levels." (PMID 34215245, 2021). "Subdoligranulum has been found to be enriched in type 2 diabetes cases, which is inconsistent with our results, as higher CLR-transformed abundance predicts lower values for 2-h insulin." (PMID 33594006, 2021). "Type 2 diabetes mellitus (T2DM) is a metabolic disease characterized by hyperglycemia due to alterations in the production and action of the hormone insulin, which is related to neuropathy and cardiovascular comorbidities." (PMID 34640404, 2021). "An estimation of global insulin requirements for type 2 diabetes between 2018-30 suggests that if insulin becomes widely available and is used appropriately to achieve HbA1c of less than 7%, approximately 15.5% of people with T2D worldwide will require insulin therapy." (PMID 33950566, 2021). "Type 2 diabetes mellitus (T2DM) is a metabolic disorder disease and is characterized by an imbalance of blood glucose levels due to defects in insulin secretion." (PMID 34356827, 2021). "As the Abl kinase inhibitor imatinib was previously shown to reverse type 2 diabetes and to inhibit VEGF signaling via Abl kinases, we studied the effect of imatinib on vascular insulin sensitivity and fatty acid transport in vivo and in vitro." (PMID 34214082, 2021). "In fact, these ‘metabolic amplification’ pathways may act early to set the amplitude of glucose‐induced secretory responses – and reduced efficacy of this pathway may contribute to impaired insulin secretion in type 2 diabetes (T2D)." (PMID 32339440, 2020). "The pathogenesis of GDM is still not fully understood, but it is very similar to that of type 2 diabetes mellitus (T2DM), which abnormal pancreatic insulin release and insulin resistance (IR) being involved." (PMID 33122744, 2020). "The reduced GAPDH acetylation was also observed in the liver of obesity and type 2 diabetes mouse models, and key lysine residues in GAPDH contribute to the regulation of glucose tolerance and sensitivity to glucagon and insulin." (PMID 33043000, 2020). "Hyperinsulinemia and deregulated insulin signaling occur in obesity, type 2 diabetes and NAFLD, and insulin activates PI3K/Akt signaling, a key regulator of metabolism, cell growth and cell survival." (PMID 32443737, 2020). "People with uncontrolled type 2 diabetes (T2DM) often delay initiating and titrating basal insulin." (PMID 32118347, 2020). "In this study, we measured serum glucose and insulin levels, insulin and glucose tolerance, and glycemia AAC and AUC as characteristics of type 2 diabetes." (PMID 33142995, 2020). "We previously reported the 24‐hr glucose, insulin, and glucagon responses to a 72‐hr fast and to a 72‐hr macronutrient sufficient, no carbohydrate (CHO), high‐fat diet (CHO‐free diet) in men with type 2 diabetes (Nuttall, Almokayyad, & Gannon, 2015)." (PMID 33030304, 2020). "In type 2 diabetes mellitus (T2DM), peripheral insulin resistance together with compensatory insulin hypersecretion from pancreatic islets likely results in some complications, such as neuropathy, nephropathy, atherosclerosis, and retinopathy." (PMID 33519360, 2020). "The study reported by Williams found lower expression of the HLA-DRB1 mRNA in type 2 diabetes, which was consistent with our findings, and suggests that HLA-DRB1 is protective for type 2 diabetes by increasing insulin secretion." (PMID 32455133, 2020).
type 2 diabetes (continued). "The distinction between type 1 and 2 developed gradually over the next five decades along with the realisation that insulin levels may be normal or raised in type 2 diabetes (T2D) and that a substantial population of β-cells survives lifelong." (PMID 33365205, 2020). "Furthermore, type 2 diabetes may also alter the effects of lifestyle interventions on tissue-specific GC metabolism compared to lifestyle changes among obese patients with normal insulin sensitivity." (PMID 32069218, 2020). "Type 2 diabetes patients with NAFLD often suffered from glucose and lipid metabolism disorder, and present with abnormally high fasting blood glucose, fasting insulin and HOMA-IR." (PMID 32762728, 2020). "It is known that growth factors such as insulin, IGF-1 and HGF support beta cell growth and survival, but in people with type 2 diabetes the destructive effects of metabolic stress predominate and beta cell death or dysfunction occurs." (PMID 32978479, 2020). "In patients with type 2 diabetes (T2DM), an impaired insulin response to GLP-1 and GIP contributes to hyperglycemia." (PMID 32308645, 2020). "This study is aimed at establishing models of obese type 2 diabetes in vitro and in vivo, observe the effect of MNAM on hepatic insulin sensitivity and glucose metabolism, and explore the regulation of the SIRT1/FOXO1 pathway." (PMID 32280711, 2020). "Ly6Chigh monocytes were FACS-purified from six groups of male mice consisting of type 2 diabetes model db/db mice, streptozotocin (STZ) induced insulin depletion mice, high fat diet (HFD) induced obesity mice and each control mice." (PMID 32097444, 2020). "Obesity promotes type 2 diabetes and nonalcoholic fatty liver disease (NAFLD), prompting us to assess insulin sensitivity and hepatic lipid content." (PMID 32251290, 2020). "During the onset of type 2 diabetes, excessive dietary intake of saturated NEFA and fructose lead to impaired insulin production and secretion by insulin-producing pancreatic beta cells." (PMID 31796987, 2020). "Maternal obesity, related to unhealthy diet and lifestyle, can negatively affect insulin sensitivity leading to the development of GDM and type 2 diabetes (T2D), with serious short and long-term health consequences for both the mother and the offspring." (PMID 33080891, 2020). "The control group had significantly lower Body Mass Index (BMI), waist circumference, blood pressure, fasting glucose and insulin concentrations, HOMA-IR, concentration of HbA1c, and C-reactive protein (CRP) than patients with type 2 diabetes." (PMID 32012942, 2020). "In support, some studies have reported reduced plasma levels of MOTS-c in people with obesity, type 2 diabetes or impaired coronary endothelial function, and exogenous MOTS-c treatment restores skeletal muscle insulin sensitivity in mice." (PMID 32182209, 2020). "As inhibition of DPP-4 prolongs the life of incretins (GLP-1 and GIP), which in turn induce insulin secretion, many DPP-4 inhibitors like sitagliptin and vildagliptin are emerging as powerful adjuncts in the treatment of type 2 diabetes." (PMID 32282828, 2020). "In type 2 diabetes, disrupted MAM interface or function has been mostly studied in the main insulin target tissues (i.e., liver and skeletal muscle) as well as in pancreatic beta cells, but not in the heart." (PMID 33258101, 2020). "Firstly, Spearman’s correlation was performed to analyze the simple correlation between plasma CTSD levels/activity and metabolic parameters of type 2 diabetes (plasma FFA and insulin)." (PMID 33101209, 2020). "One reason that insulin-treated pregestational diabetes had a higher effect size than type 2 diabetes (not treated with insulin) on the risk that offspring will have an ICD-10 F code diagnosis might be that mothers with insulin-treated pregestational diabetes have poorer glucose control." (PMID 32031649, 2020).
type 2 diabetes (continued). "The combination of Ganmaidazao and Shengmai-Yin decoction is applied as adjuvant therapy for Type II diabetes mellitus via activation of HSL, PPARα, and AMPK/PI3K/AKT, and inhibition of SREBP-1/FAS, influencing insulin sensitivity, and lipid biosynthesis." (PMID 32477116, 2020). "Women who received insulin treatment for GDM had a higher probability of subsequent diagnosis of both type 1 and type 2 diabetes." (PMID 32725280, 2020). "We included 66,088 individuals with type 2 diabetes from seven waves of data collection; of these, 42,171 (63.8%) received OGLD only, 14,529 (22.0%) received OGLD + insulin and 7566 (11.4%) received insulin only." (PMID 31901950, 2020). "For heredity of type 2 diabetes, 3-MOB was a strong predictor along with glucose tolerance and insulin sensitivity." (PMID 32561768, 2020). "Blood glucose, plasma insulin, and glucagon levels were measured following a duodenal glucose tolerance test (IDGTT), in four pigs with STZ-induced type 2 diabetes (T2D pigs) and in four pigs with STZ-induced type 1 diabetes (T1D pigs)." (PMID 33294459, 2020). "AzA administration reduced plasma glucose, insulin, liver glycogen and key carbohydrate metabolic enzymes in HFD-induced type 2 diabetic mice." (PMID 32411005, 2020). "The pathogenesis of Type II diabetes mellitus (T2DM) is mainly attributed to IR, the functional defect of islet β cells, and the relative insufficiency of insulin." (PMID 32265719, 2020). "Several studies have demonstrated the insulin-sensitizing role of myo-inositol in conditions such as PCOS, post-menopausal metabolic syndrome, type 2 diabetes, and GDM." (PMID 32646482, 2020). "Already a therapeutic target for type 2 diabetes (T2D), GLP-1 is an integral signaling hormone responsible for promoting insulin secretion and satiety while decreasing glucagon secretion and gastric emptying." (PMID 32051237, 2020). "It has been reported that HSL activity is reduced in adipose tissue of patients with type 2 diabetes, and HSL protein expression is reduced in obese insulin-resistant states." (PMID 34026301, 2020). "Selenium supplementation has been shown to improve insulin concentrations and HOMA-IR in people with type 2 diabetes and coronary heart disease." (PMID 33066009, 2020). "PPAR-γ is a target of insulin sensitivity, involved in obesity, NAFLD, NASH, and type 2 diabetes mellitus (T2DM)." (PMID 32733933, 2020). "Interestingly, apoC-II, which to our knowledge has not been investigated for association with incident type 2 diabetes to date, showed the strongest positive associations with fasting glucose, fasting insulin and HOMA-IR of all investigated apolipoproteins in the present study." (PMID 30599058, 2019). "In type-II diabetes (T2DM), cells become resistant to insulin signalling, failing to respond to it sufficiently." (PMID 30671675, 2019). "Variable rate intravenous insulin infusion was used during the initial up-titration of the ETF for patients with type 1 diabetes and in patients with type 2 diabetes who had severe hyperglycemia." (PMID 30931197, 2019). "Assessing attitudes toward insulin injection may help in the design of interventions that improve the insulin injection behaviors of patients with type 2 diabetes (T2DM)." (PMID 30807441, 2019). "In this review, we discuss the role of insulin and the INSR in the development and endocrine activity of adipose tissue and the pharmacological implications for the management of obesity and type 2 diabetes." (PMID 30754657, 2019). "Dipeptidyl peptidase IV (DPPIV) is known to play a role in type 2 diabetes by breaking down GLP-1, which in turn regulates glucose-dependent insulin secretion." (PMID 31164969, 2019). "In later stages of type 2 diabetes, DPP-4 inhibitors are also recommended in the guidelines in triple therapies with metformin and SGLT-2 inhibitors or with metformin and insulin." (PMID 31275246, 2019).
type 2 diabetes (continued). "Compared to patients with type 2 diabetes, those with LADA have less insulin secretion and progress to insulin dependence faster." (PMID 30971952, 2019). "To investigate the involvement of autophagy in kisspeptin–regulated insulin secretion, we overexpressed Kiss1 in NIT-1 cells to mimic the long-term exposure of pancreatic β-cells to kisspeptin during type 2 diabetes (T2D)." (PMID 31767891, 2019). "PTP1B has a prominent role in the metabolism, through the regulation of insulin signaling, leading to the development of PTP1B inhibitors for the treatment of type 2 diabetes or obesity." (PMID 31737637, 2019). "For instance, SOCS1 degrades IRS1 and IRS2, required for insulin signaling, via the SOCS Box domain, thus, limiting its potential in type-2 diabetes." (PMID 31105556, 2019). "We measured PG and INS levels at 0, 30, 60, and 120 minutes during an OGTT in 543 participants in the Botnia Prospective Study, 146 of whom progressed to type 2 diabetes within a 10-year follow-up period." (PMID 30445509, 2019). "In conclusion, our results showed for the first time that M. quadrangula extract improves insulin sensitivity and glucose tolerance in HFD/STZ type 2 diabetic rats." (PMID 30915195, 2019). "The results suggest that type 2 diabetes promotes centrosome amplification via ROCK1 and 14‐3‐3σ, with high glucose, insulin, and palmitic acid as the triggers." (PMID 30478982, 2019). "While insulin-stimulated muscle GLUT4 translocation and glucose transport is impaired in type 2 diabetes, the ability of acute bouts of exercise or muscle contractile activity to stimulate GLUT4 translocation and glucose transport remains intact." (PMID 31614762, 2019). "Further studies showed that GLP-1 stimulates insulin secretion also in type 2 diabetes and that overnight GLP-1 infusion reduces glucose levels in type 2 diabetes." (PMID 31275243, 2019). "Some animal-based studies have shown anti-hyperglycemic properties of RSV, and patients with type 2 diabetes mellitus (T2DM) exhibited reduced oxidative stress, as well as improved insulin sensitivity and cardiovascular function after RSV treatment." (PMID 31480513, 2019). "FFA1 has been recognized to mediate insulin secretion in a phospholipase C- (PLC-) dependent manner; hence, it plays an important role in type 2 diabetes mellitus." (PMID 30863781, 2019). "Studies revealed an impaired insulin-stimulated phosphorylation of IRS-1 and a decrease of PI3K activity in the muscle from obese and type 2 diabetes." (PMID 31847151, 2019). "On the other hand, insulin was observed to suppress MCP-1, sICAM-1, and TF in normal obese subjects and obese patients with type 2 diabetes mellitus." (PMID 31052277, 2019). "The aim of this study was to evaluate the correlation between the resistance index SPISE-IR (defined as 10/SPISE) and the euglycemic insulin clamp, and to estimate the effect of SPISE-IR as a predictor for risks of future CHD and manifest type 2 diabetes." (PMID 31694444, 2019). "The activation of cPKCβII is increased in endothelial cells of patients with type 2 diabetes, and cPKCβ inhibitor LY379196 improved insulin-mediated eNOS activation." (PMID 31521120, 2019). "We performed a randomized crossover study among type 2 diabetes (T2DM) patients with ESRD on continuous hemodialysis and receiving standard insulin for glycemic control." (PMID 31828166, 2019). "Here, we aimed to determine the effects of IOE on insulin signaling and GLUT4 expression in db/db mice and to compare them with those of metformin, the first-line drug for the treatment of type 2 diabetes." (PMID 31323977, 2019). "For example, in a model of diet-induced type 2 diabetes, NMN restored insulin signaling and ameliorated oxidative stress and inflammation by activating Sirtuin 1 (SIRT1)." (PMID 31823815, 2019).